SPI1 (Spi-1 proto-oncogene)
Diseases named in the same sentence as SPI1 in open-access papers (continued):
Sharing a sentence is not in itself a finding about the gene and the disease.
melanoma (10 papers, 2019 to 2025). A malignant, usually aggressive tumor composed of atypical, neoplastic melanocytes. "Here, we present the mechanism underlying the effect of SPI1 in regulating the biological behaviour of melanoma cells." (PMID 37539493, 2023). "We speculated that SPI1 might be a pathogenic factor for melanoma, and specific research studies on this subject have yet to be conducted." (PMID 37539493, 2023). "Given this evidence and the results of this study, the patients with the “low-expressing” SPI1 allele could potentially have increased sensitivity to self-antigens, what may allow for improved clearing of “micro” melanomas before they developed into detectable MPMs48." (PMID 31308438, 2019). "qRT–PCR assays were conducted to determine the mRNA expression of SPI1 in 30 melanoma tissues and normal adjacent tissues." (PMID 37539493, 2023). "In general, our work indicated that the transcription factor SPI1 promoted melanoma cell proliferation, metastasis and glycolysis by promoting HK2 expression and activating the AKT1/mTOR signalling pathway." (PMID 37539493, 2023). "Altogether, our work elucidated that downregulation of SPI1 hampered cell proliferation, metastasis and glycolysis in melanoma cells by blocking the AKT1/mTOR axis by targeting HK2." (PMID 37539493, 2023). "SPI1 knockdown restrained melanoma cell proliferation, metastasis and glycolysis by regulating the AKT1/mTOR pathway." (PMID 37539493, 2023). "SPI1 transcription in melanoma tissues was dramatically higher than that in adjacent normal tissues." (PMID 37539493, 2023). "Methylation reactions in the TME of melanoma impact the expression of B2M and SPI1, which controls CD1D expression." (PMID 37077920, 2023). "The CCK‐8 assay revealed that restrained melanoma cell viability due to sh‐SPI1 transfection was abrogated by HK2 overexpression." (PMID 37539493, 2023). "Immunohistochemical detection showed that SPI1‐positive cell numbers in melanoma tissues were markedly enhanced." (PMID 37539493, 2023). "SPI1 transcription in melanoma cells and tissues was dramatically higher than that in adjacent normal tissues and epidermal melanocyte HEMa‐LP, respectively." (PMID 37539493, 2023). "Overexpression of HK2 weakened the inhibitory effects of SPI1 knockdown on the viability, metastasis and glycolysis of melanoma cells." (PMID 37539493, 2023). "We identify that NLRC5 is expressed in both immune cells and melanoma cells in melanoma samples and its expression is regulated by SPI1 and DNA methylation." (PMID 34307322, 2021). "Single-cell RNA sequencing analysis of GSE72056 and GSE115978 showed that SPI1 is expressed in macrophages, B cells, T cells, and malignant melanoma cells in melanoma samples." (PMID 34307322, 2021). "In particular, ELK3, ETS1, ETV1, ETV4, ETV5, and SPI1 were significantly upregulated in melanoma, whereas EHF, ELF3, ELF5, ERG, ETS2, ETV7, and SPDEF were significantly downregulated in the tumor." (PMID 33424867, 2020). "Similarly, the mRNA expression levels of SPI1 in melanoma cell Lines A375, A2058, B16 and MUM2B were obviously higher than those in epidermal melanocyte HEMa‐LP and were highest in A375 and MUM2B cells." (PMID 37539493, 2023). "Herein, we validated that SPI1 levels were strikingly elevated in melanoma cells and tissues and that SPI1 knockdown could restrain cell proliferation, metastasis and glycolysis in melanoma cells." (PMID 37539493, 2023). "Our work aimed to investigate the potential regulatory mechanism of SPI1 in melanoma." (PMID 37539493, 2023). "Knockdown of SPI1 restrained cell viability, metastasis and glycolysis in melanoma cells." (PMID 37539493, 2023). "Furthermore, subsequent experiments indicated that HK2 overexpression weakened the inhibitory effect of SPI1 knockdown on cell viability, metastasis and glycolysis in melanoma cells." (PMID 37539493, 2023).
melanoma (continued). "Future investigations may focus on the transcription factor‐DNA networks for SPI1 and the mechanisms involved in melanoma based on the findings of the present study." (PMID 37539493, 2023). "Moreover, the SPI1 protein level was markedly increased in melanoma cells and was highest in A375 and MUM2B cells." (PMID 37539493, 2023). "Moreover, Kaplan-Meier analysis of SPI1 expression in melanoma datasets showed that low expression of SPI1 was significantly associated with poor OS, DSS, and PFI in melanoma patients." (PMID 34307322, 2021). "In melanoma, several ETS TFs, including FLI1, SPI1, ELF4, ETV7, SPIB, and SPIC, are expressed at higher levels in Cluster A patients, whereas ETV5, ETV4, ELK1, ERF, and ETV2 showed increased expression in Cluster B patients." (PMID 41502516, 2025). "The 12 TFs that were inferred to regulate NK and T cells activation in these modules are shown as follows: Module M1 contained the regulators IRF1, STAT1, SPI1, FLI1, IRF7, and E2F1, which are essential regulators for C4 Melanoma CORO1A." (PMID 37435067, 2023). "Herein, we verified that SPI1 regulated HK2 expression, thereby mediating the AKT1/mTOR signalling pathway and promoting melanoma cell proliferation, metastasis and glycolysis." (PMID 37539493, 2023). "The findings in our study suggested that SPI1 interacted with HK2 and positively regulated its expression to promote melanoma progression." (PMID 37539493, 2023). "In addition, we found that NLRC5 expression positively correlated with transcription factor SPI1 expression in 28 kinds of tumor samples from TCGA including TCGA SKCM, which was also consistent with melanoma datasets from the GEO Platform (GSE54467, GSE59455, and GS65904)." (PMID 34307322, 2021). "We provide further evidence that epigenetic changes in the TME of melanoma tumors have a direct impact on B2M and an indirect impact on CD1D gene expression (through SPI1) but not on CD1B and FCGRT expression in melanoma patients from the TCGA dataset." (PMID 37077920, 2023).
Obesity (10 papers, 2014 to 2023). Accumulation of substantial excess body fat. "We further utilized our model to query the effects of a novel obesity therapeutic target, the transcription factor SPI1." (PMID 25409310, 2014). "We utilized our model to query the effects of a novel obesity therapeutic target, the transcription factor SPI1." (PMID 25409310, 2014). "After validating our clonal cell line and automated analysis scheme, we tested the effect of a reduction in Spi1 mRNA, a transcription factor with a potential role in obesity." (PMID 25409310, 2014). "Taken together these data indicate that SPI1 could play a role in adipogenesis, and subsequently in the development of obesity." (PMID 25409310, 2014).
B-cell lymphomas (9 papers, 2017 to 2025). "Similarly, exposure to TK-216, the clinical derivative of YK-4-279, reduced the interaction of ETS factors SPIB and SPI1 with these RNA helicases in B-cell lymphomas." (PMID 34221969, 2021).
diabetes (9 papers, 2016 to 2025). "Excessive AGEs in diabetes promote the upregulation of copper importer SLC31A1 through ATF3/SPI1, thereby increasing intracellular copper accumulation in cardiomyocytes and disturbing copper homeostasis." (PMID 39415790, 2024). "Our findings showed, for the first time, that excessive AGEs and copper in diabetes upregulated ATF3/SPI1/SLC31A1 signaling, thereby disturbing copper homeostasis and promoting cuproptosis." (PMID 36675183, 2023). "The excessive increase in AGEs and copper in diabetes induced the upregulation of copper importer SLC31A1 through ATF3/SPI1, thereby mediating the accumulation of copper in cardiomyocytes, disturbing copper homeostasis and promoting cuproptosis." (PMID 36675183, 2023). "Hoxa3-treated mφs showed upregulation of maturation markers F4/80 and CD115 as well a master regulator of mφ development, Spi1/Pu.1, at both transcriptional and protein levels, thus supporting the hypothesis that Hoxa3 rescues diabetes-induced mφ maturation defects." (PMID 27342843, 2016). "SPI1 and MTF1 were two novel upstream ΤFs identified which have been suggested to be involved in the inflammatory cascade and insulin regulation in diabetes." (PMID 39974596, 2025). "Key examples include IRF1, GATA6, SPI1, EPAS1, NFKB2, and STAT5B, which are involved in immune response, cell differentiation, and metabolic regulation, all of which are critical in diabetes pathogenesis." (PMID 39877357, 2024). "SPI1 and MTF1 were two novel upstream transcription factors identified which have been suggested to be involved in the inflammatory cascade and insulin regulation in diabetes." (PMID 39974596, 2025). "Our data indicated that ATF3 and/or SPI1 might be upstream of SLC31A1 and regulate cuproptosis of cardiomyocytes in diabetes." (PMID 36675183, 2023).
salmonellosis (9 papers, 2009 to 2024). Infections with bacteria of the genus salmonella. "In our study, we show that growth in LB to late exponential phase resulted in higher transcript abundances of SPI-1 genes in strains representing S. Javiana as compared to S. Typhimurium; both of these serovars are frequently associated with human clinical salmonellosis." (PMID 34721328, 2021). "A study comparing environmental isolates of Salmonella Newport with clinical Salmonella Typhi from a region where salmonellosis is endemic also reported the occurrence of SPI-1 to SPI-6 in 95%–100% of the isolates." (PMID 37041837, 2023). "The pathogenicity of Salmonella is mainly dependent upon the two Salmonella encoded T3SSs (Type III Secretion systems), i.e. SPI-1 and SPI-2, which are required for different stages of salmonellosis, namely cell invasion and intracellular replication." (PMID 35273308, 2022). "SPI-1 affects the whole process of salmonellosis, including pathogen invasion, proliferation, and host responses." (PMID 31428589, 2019). "Similarly, deletion of avrA gene was observed in SPI-1 of Salmonella Enteritidis isolated from poultry and salmonellosis outbreaks, as well as in serovars Typhi, Paratyphi, and Arizonae." (PMID 37041837, 2023). "In addition, S. Cerro, a serovar that is considerably less common among human clinical salmonellosis cases, showed lower SPI-1 transcript abundances than either S. Javiana or S. Typhimurium." (PMID 34721328, 2021). "Hence, the role of the SPI-1 factors in bacterial pathogenesis, especially during the late stages of salmonellosis, needs further characterization and their expression in vivo needs to be studied." (PMID 19371445, 2009). "In this study, we have constructed bacterial strains that contain a FLAG epitope inserted in frame to SPI-1 genes prgI, sipA, sipB, sopE2, spaO, and sptP, and investigated the expression of the tagged proteins both in vitro and in vivo during murine salmonellosis." (PMID 19371445, 2009). "In this study, we constructed Salmonella strains that contained a FLAG epitope sequence inserted in frame into the carboxyl terminus of SPI-1 genes prgI, sipA, sipB, sopE2, spaO, and sptP, and characterized the expression of the tagged proteins in vitro and in vivo during murine salmonellosis." (PMID 19371445, 2009). "The aim of this study was to evaluate the effect of the deletion of SPI-1 or SPI-2 genes on the intestinal and systemic salmonellosis using the avian model." (PMID 37490241, 2024). "The activities of this compound against Salmonella showed that it is possible to be a potential candidate for anti-SPI-1 T3SS substance, likely combined with other agents, to use as a novel anti-salmonellosis agent." (PMID 35380331, 2022).
asthma (8 papers, 2015 to 2025). "That Asthma 3’s plasma blast cells show a duality of T cell identity could be linked to the SPI1’s aberrant expression pattern." (PMID 41550933, 2025). "This study demonstrates that SPI1 is important in HDM-induced experimental asthma and that its pharmacological inhibition reduces HDM-induced airway collagen deposition and hyperresponsiveness." (PMID 36698141, 2023). "We also demonstrate that SPI1 is important in HDM-induced experimental asthma pathogenesis and that its pharmacological inhibition reduces HDM-induced collagen deposition and AHR." (PMID 36698141, 2023). "To assess the functional effects of targeting SPI1 on HDM-induced experimental asthma, we measured AHR following treatment with DB1976 and DB2313 throughout the model." (PMID 36698141, 2023). "Then, to assess the effects of therapeutically targeting SPI1 on HDM-induced experimental asthma, we administered DB1976 and DB2313, that interact with the DNA minor groove that flanks the PU.1 binding motif to inhibit its activity, throughout the model." (PMID 36698141, 2023). "SPI1 might influence the developmental fate of plasma blast cells in Asthma 3 and further exacerbate the patient’s symptoms." (PMID 41550933, 2025). "In Asthma 1 and Asthma 2, the expression dynamics of JUN, SPI1 and six inflammatory response related genes are almost the same." (PMID 41550933, 2025). "They include RBM42, STX5, and TRIM41 in asthma, CYP27A1, GM2A, LGALS9, SPI1, and NLRC4 in COPD, as well as ATF3, PPP1R15A, ZFP36, SOCS3, NAMPT, and GADD45B in IPF." (PMID 31952466, 2020). "In Asthma 1 and Asthma 2, the repression of JUN seems to be replaced by the expression of SPI1." (PMID 41550933, 2025). "In Asthma 3, the beginning of the expression of SPI1 is consistent with that in healthy controls, but the expression of SPI1 shows no decline like healthy controls." (PMID 41550933, 2025). "In human asthma-associated CD4 T cells, SPI1 (the gene encoding PU.1) is notably not upregulated in Th2 cells, even when analysis is focused on those cells producing IL-9." (PMID 37163370, 2023). "Previous studies have found that both TNF, SPI1, and CCR7 were up-regulated in severe asthma." (PMID 35645813, 2022). "These genes included RBM42, STX5, and TRIM41 in asthma, CYP27A1, GM2A, LGALS9, SPI1, and NLRC4 in COPD, ATF3, PPP1R15A, ZFP36, SOCS3, NAMPT, and GADD45B in IPF, LRRC48 and CETN2 in asthma-COPD, COL15A1, GIMAP6, and JAM2 in asthma-IPF and LMO7, TSPAN13, LAMA3, and ANXA3 in COPD-IPF." (PMID 31952466, 2020).
cervical cancer (8 papers, 2021 to 2025). A primary or metastatic malignant neoplasm involving the cervix. "For example, the METTL3/circSTX6/SPI1 feedback loop plays an important role in cervical cancer, and drug development targeting this loop is expected to be a new direction for cervical cancer treatment." (PMID 40458727, 2025). "A previous study discovered that lncRNA small nucleolar RNA host gene 16 upregulated poly(ADP-ribose) polymerase family member 9 expression by recruiting the transcription factor, SPI1, to promote the tumorigenicity of cervical cancer cells." (PMID 34738863, 2021). "For example, SNHG16 can recruit the SPI1 protein to promote the transcriptional activation of the PARP9 promoter in cervical cancer." (PMID 37303939, 2021). "Previous study shows that SNHG16 can combine with transcription factor SPI1 to upregulate PARP9 transcription to further promote tumorigenicity of cervical cancer." (PMID 37303939, 2021). "Correlation analysis revealed that HSF1 is lowly expressed in cervical cancer, and ROS can promote the expression of HSF1, which in turn promotes the expression of PU.1 (SPI1), and PU.1 (SPI1) promotes the expression of Dectin1 (CLEC7A)." (PMID 40399470, 2025). "LncRNA SNHG16 recruits the transcription factor SPI1 to promote the transcription of PARP9, thereby promoting the tumorigenicity of cervical cancer cells." (PMID 35771155, 2022).
enteritis (8 papers, 2008 to 2024). Inflammation of the small intestine. "The type III protein secretion system (T3SS) encoded by Salmonella pathogenicity island 1 (SPI-1) delivers effector proteins required for intestinal invasion and the production of enteritis." (PMID 31428589, 2019). "The two T3SSs, encoded by SPI-1 and SPI-2, secrete effectors into the host cell to cause numerous events that result in symptoms of human enteritis." (PMID 37325511, 2023). "The SPI-1 and the SPI-2 play a potential role in intestinal invasion and development of enteritis, since they encode type III secretion systems (T3SS)." (PMID 36297250, 2022). "The Salmonella SPI-1 (located within C63PI) and the SPI-2 encode type III secretion systems (T3SS), which are required for intestinal invasion and the production of enteritis." (PMID 34451486, 2021). "The SPI-1 genes mediate Salmonella invasion of cells at the intestinal epithelium, which generates enteritis, whereas the SPI-2 genes primarily mediate Salmonella replication within host cells." (PMID 34048498, 2021). "These genes, particularly those associated with the Salmonella pathogenicity island 1 (SPI-1) and Salmonella pathogenicity island 2 (SPI-2) type III secretion systems, have been well-characterised for their role in both enteritis and systemic infection in mammalian models." (PMID 18230128, 2008). "Furthermore, our results are also consistent with reports indicating that SPI-1 or HilD function is required to invade cells from the intestinal epithelium, and thus to induce enteritis, but not to colonize the cecum lumen." (PMID 34048498, 2021). "Their results show that although SPI-1 is important for the induction of enteritis early in infection, SPI-2 has a more important role in the pathogenesis of enteritis because it is required regardless of the presence of SPI-1." (PMID 37490241, 2024).
gastric cancer (8 papers, 2021 to 2025). A primary or metastatic malignant neoplasm involving the stomach. "SPI1 expression was markedly enhanced in gastric cancer, and high SPI1 expression was related to poor prognosis and tumour progression." (PMID 37539493, 2023). "Correlations between SPI1 mRNA expression and clinical prognosis in gastric cancer with different clinicopathological factors using Kaplan–Meier analysis." (PMID 35237521, 2022). "Recent studies have shown that SPI1 may be a crucial oncogenic transcription factor promoting the progression of various cancers, including liver cancer, gastric cancer and ovarian cancer." (PMID 41372608, 2025). "Current studies on KLF5 in gastric cancer have been extensive, but the role of SPI1 is still unknown." (PMID 36967718, 2023). "Therefore, we have reason to believe that SPI1, as a key regulator of immune signal transduction, can promote the progression of gastric cancer by regulating the composition and proportion of tumor infiltrating immune cells." (PMID 35237521, 2022). "SPI1 can be a prognostic marker and immunotherapeutic target for gastric cancer patients." (PMID 36477668, 2022). "However, the potential role of SPI1 in gastric cancer (GC) and the correlations between SPI1 and immune infiltration remain unclear." (PMID 35237521, 2022). "In gastric cancer, NR2F1-AS1 acts as an EMT-inducing lncRNA that enhances cell motility via the miR-29a/VAMP7 axis, activation of AKT3 through miR-190a/PHLDB2, SPI1-mediated transcriptional upregulation of ST8SIA1, and miR-493-5p/MAP3K2 signaling." (PMID 40828427, 2025). "In gastric cancer, NR2F1-AS1 enhances cell growth through various axes, including miR-29a/VAMP7, miR-190a/PHLDB2/AKT3, SPI1/ST8SIA1, and miR-493-5p/MAP3K2." (PMID 40828427, 2025).
lung cancer (8 papers, 2021 to 2025). A malignant neoplasm involving the lung. "SPI1-induced upregulation of lncRNA SNHG6 promotes nonsmall-cell lung cancer via miR-485-3p/VPS45 axis." (PMID 36967718, 2023). "To further explore the mechanism of MNDA down-regulation in LA, we predicted that SPI1 is the transcriptional regulator of MNDA, that SPI1 is significantly down-regulated in lung cancer, and that MNDA expression increases with the increase in SPI1 expression." (PMID 36101427, 2022). "Although we found that both perforin and granzyme B were significantly less expressed at mRNA level in patients with lung cancer, PRF1, but not GRZMB, positively correlated with SPI1 mRNA expression in both cohorts." (PMID 40895524, 2025).